GPX1 (glutathione peroxidase 1)
Diseases named in the same sentence as GPX1 in open-access papers (continued):
Sharing a sentence is not in itself a finding about the gene and the disease.
malaria (3 papers, 2014 to 2023). Malaria is a serious and sometimes fatal disease caused by a parasite that commonly infects a certain type of mosquito which feeds on humans. "Eleutherin and isoeleutherine were the ones that presented the lowest binding energy for CAT, GR, and GPx1, showing themselves to be possible targets of these molecules in the involvement of the redox balance during malaria." (PMID 37513429, 2023). "Additionally, co-expression analysis identified a correlation between glutathione peroxidase 1 (GPX1, NP_001130041.1) and WBC concentrations where GPX1 and additional glutathione-related transcripts had increased expression in response to malaria." (PMID 30518325, 2018). "The set of proteins that was denoted ‘Malaria decreased’ contained fibulin-1 (FBLN1) and RANTES (CCL5), both involved in endothelial cell death, whilst glutathione peroxidase (GPX1) protects from oxidative stress." (PMID 24743550, 2014).
myocarditis (3 papers, 2015 to 2023). Myocarditis is a condition that is characterized by inflammation of the heart muscle (myocardium). "The benign CVB3/0 strain caused myocarditis in mice with an abnormal selenoenzyme (GPx1) gene." (PMID 37946846, 2023). "Mice with a disrupted gpx1 gene infected with CVB3/0 compared with wild type mice with an intact gpx1 gene experienced myocarditis, and sequencing of the viruses from the mice with disrupted gpx1 gene showed seven nucleotide changes in the Coxsackie virus." (PMID 35008706, 2021). "GPx deficiency has been linked to mutation of coxsackie virus B3 viral genome, with replacement of G base (most vulnerable to oxidation) at three of the seven sites, and enhanced myocarditis in Gpx1-/- mice, though authors did not conclude enhanced viral burden." (PMID 26075398, 2015).
oral cancer (3 papers, 2015 to 2023). "In the current study, antioxidant gene expressions (NFE2L2, SOD1, TXN, GSR, CAT, and GPX1) in oral cancer Ca9-22 and CAL 27 cells were highly downregulated by UVC/sinularin combined treatments compared to the separate treatments." (PMID 34070049, 2021). "It was found that ED-71 is able to significantly inhibit the proliferation and migration of oral cancer cells (SCC-15 and CAL-27), block the cell cycle in the G0/G1 phase, and enhance apoptosis through glutathione peroxidase-1 (GPX1) downregulation." (PMID 37299554, 2023). "Accordingly, the gene expressions of antioxidant genes such as NFE2L2, SOD1, TXN, GSR, CAT, and GPX1 were evaluated by qRT-PCR following UVC and/or sinularin treatments in oral cancer cells (Ca9-22 and CAL 27)." (PMID 34070049, 2021).
schizophrenia (3 papers, 2022 to 2025). A major psychotic disorder characterized by abnormalities in the perception or expression of reality. "GPX-1 polymorphisms rs1050450 and rs1800668 have been associated with schizophrenia in the Chinese population, suggesting a potential role of GPX-1 gene in psychosis." (PMID 35741861, 2022). "Blood biochemical markers GPX1, MDA1, CAT1, and TNF-α may play an important role in the pathogenesis of schizophrenia combined with TD patients, and they may be useful in the diagnosis of schizophrenia with tardive dyskinesia." (PMID 35299866, 2022).
skin tumor (3 papers, 2013 to 2019). "Overexpression of GPX1 increased the number of tumors and promotes their growth in a mouse model of skin cancer." (PMID 31844035, 2019). "In a mouse model of skin cancer, overexpression of GPX1 increased the number of tumors and promotes their growth." (PMID 31844035, 2019). "However, higher levels of GPx have also been found to have procarcinogenic activity as demonstrated by enhanced skin tumor incidence in transgenic mice overexpressing Gpx1." (PMID 23691100, 2013).
steatosis (3 papers, 2021 to 2024). Increased lipid within the cytoplasm of cells. "Amongst the 13 genes, eight (DIO1, GPX2, SEPHS2, SELENOK, SELENOS, SELENOT, SELENOF, and SELENOW) had higher, and five (DIO3, GPX1, SELENON, SELENOO, and TXNRD3) had lower expression in steatosis." (PMID 34869521, 2021). "Of these genes, 11 coded for selenoproteins of which four genes had lower expression (SELENON, SELENOO, GPX1, and TXNRD3) and seven genes had higher expression (SELENOK, SELENOS, SELENOW, GPX2, GXP3, DIO1, and SEPHS2) in steatosis." (PMID 34869521, 2021).
thyroid tumor (3 papers, 2022 to 2023). A benign or malignant neoplasm affecting the thyroid gland. "In contrast, other studies reported that GPx1 expression is reduced in thyroid tumors, and associated with an increased level of free radicals in the tumor tissue." (PMID 36497339, 2022). "Similarly, upregulated GPX1 expression has also been reported in thyroid tumours, although decreased GPx1 expression was observed through protein expression analyses." (PMID 37692064, 2023). "On the other hand, AHNAK2, GPX1, KRT19, and SFN show higher expression levels in thyroid tumors." (PMID 37795451, 2023).
type 1 diabetes (3 papers, 2017 to 2021). "In addition our proteomic profiling data in the kidney are consistent with previous reports using type 1 diabetic animal models showing that the expression of calbindin, integrin B1, kininogen 1, haptoglobin, and glutathione peroxidase 1 are altered by the diabetic state." (PMID 29121074, 2017).
vitiligo (3 papers, 2014 to 2025). Generalized well circumscribed patches of leukoderma that are generally distributed over symmetric body locations and is due to autoimmune destruction of melanocytes. "Several investigations have shown a reduction in GPX levels in the serum and tissues of patients with vitiligo, and genetic studies indicated that GPX1 polymorphism is associated with vitiligo susceptibility." (PMID 41007740, 2025).
amyotrophic lateral sclerosis (2 papers, 2023). Amyotrophic lateral sclerosis (ALS) is a neurodegenerative disease characterized by progressive muscular paralysis reflecting degeneration of motor neurons in the primary motor cortex, corticospinal tracts, brainstem and spinal cord. "In amyotrophic lateral sclerosis, hnRNPK binds to antioxidant NFE2L2 (NFE2-like BZIP transcription factor 2) and GPX1 (glutathione peroxidase 1) transcripts." (PMID 36735291, 2023).
Balkan endemic nephropathy (2 papers, 2019 to 2023). "The association of GPX1 and SOD2 contributes to ochratoxin (OTA)-induced nephrotoxicity and Balkan endemic nephropathy." (PMID 37893028, 2023). "Interestingly, genetic polymorphism rs1050450 in GPX1, a major antioxidant enzyme responsible for hydrogen peroxide inactivation, does not seem to influence susceptibility to Balkan endemic nephropathy." (PMID 31382611, 2019).
cardiac ischemia (2 papers, 2021 to 2023). "Another study that focused on the mitochondrial dysfunction following cardiac ischemia-reperfusion injury found that deficiency of GPx1 augmented mitochondrial dysfunction post-reperfusion." (PMID 34579115, 2021). "In studies of myocardial ischemia-reperfusion injury, GPX1 KO exacerbated oxidative stress injury during myocardial ischemia-reperfusion." (PMID 36937839, 2023).
coronary atherosclerosis (2 papers, 2007 to 2016). Atherosclerosis of the coronary vasculature. "It would be interesting to investigate which observation including the properties of the plaque, calcifications and stenosis is strongly associated with the GPx-1 polymorphism as the information should provide further insights into the mechanism for development of coronary atherosclerosis." (PMID 17825092, 2007). "Thus, the reduction of erythrocyte GPX-1 activity in patients with triple vessel disease compared to double and single vessel disease indicating low GPX-1 activity could be one of the possible causesof coronary atherosclerosis in our study group." (PMID 27229152, 2016).
endotoxemia (2 papers, 2020). "Thus, we tested if endotoxemia was associated with decreased Gpx1 or Trxrd1 in the lung, kidney or spleen." (PMID 33224150, 2020). "For example, GPx1 KO mice showed an enhanced inflammatory response in comparison to WT mice during endotoxemia." (PMID 31765890, 2020).
epilepsy (2 papers, 2022 to 2025). A brain disorder characterized by episodes of abnormally increased neuronal discharge resulting in transient episodes of sensory or motor neurological dysfunction, or psychic dysfunction. "In patients with severe epilepsy, increased expression of antioxidant selenoproteins, such as SelW, GPX1, and TrxR1, in surgically removed brain tissue suggested enhanced Se utilization in epilepsy." (PMID 40873639, 2025). "Since pilocarpine reduces the total GSH level in the rat hippocampus within the acute and chronic (epilepsy) stages, it is likely that the alterations in GPx1 expression may be adaptive responses to reduced GSH levels induced by acute and chronic seizure activity." (PMID 35453441, 2022). "Considering that the total GSH level in the hippocampus is decreased at the acute and chronic (epilepsy) stages of the rat pilocarpine epilepsy model, it is presumable that reduced GSH level would affect the differential GPx1 expression in the hippocampal neurons following SE." (PMID 35453441, 2022).
esophageal cancer (2 papers, 2015 to 2017). A primary or metastatic malignant neoplasm involving the esophagus. "In many cancers, including esophageal cancer, GPx1 further induces malignancy and promotes tumor progression, effects that can be reduced by vitamin D." (PMID 26020962, 2015). "Moreover, high GPx1-expressing tumors could be responsible for cisplatin resistance as observed in esophageal cancer cell lines." (PMID 28536671, 2017).
Fungal infection (2 papers, 2017 to 2024). "Fungal infections also increase HMOX1 and COX2 expressions and inhibit the levels of antioxidant enzymes, superoxide dismutase-1 (SOD1), glutathione peroxidase-1 (GPx1), and peroxide resin-4 (PRDX4)." (PMID 39763659, 2024). "Fungal infection also increased the mRNA expression and protein production of heme oxygenase-1 (HMOX1) and cyclooxygenase-2 (COX2), with suppressed levels of antioxidant enzymes, superoxide dismutase-1 (SOD1), glutathione peroxidase-1 (GPx1) and peroxiredoxin-4 (PRDX4)." (PMID 28874754, 2017).
head and neck cancer (2 papers, 2017 to 2021). A primary or metastatic malignant neoplasm affecting the head and neck. "The association between GPx1 and patient and tumor related factors were investigated in 87 pretreatment biopsies from head and neck cancer patients treated by (chemo)radiation." (PMID 28536671, 2017). "Therefore, in this retrospective study, we investigated the prognostic value of GPx1 expression in head and neck cancers." (PMID 28536671, 2017). "Other data have shown that expression of GPX1 has no prognostic significance in head and neck cancers, however in advanced T3/4 tumors the expression was lower compared to T1/2 tumors." (PMID 34200699, 2021). "Interestingly, our results suggest the absence of the prognostic value of GPx1 expression in head and neck cancers." (PMID 28536671, 2017).
head and neck squamous cell carcinoma (2 papers, 2017 to 2021). A squamous cell carcinoma that arises from any of the following anatomic sites: lip and oral cavity, nasal cavity, paranasal sinuses, pharynx, larynx, and salivary glands. "In line with our previous studies, in which we showed a role of glutathione and associated enzymes as potential biological markers, we investigated the relationship between GPx1 and prognosis of head and neck squamous cell carcinoma." (PMID 28536671, 2017). "Therefore, in line with our previous studies pointing at the role of glutathione and associated enzymes as potential biological markers, we have investigated relationships between GPx1 and prognosis of head and neck squamous cell carcinoma (HNSCC)." (PMID 28536671, 2017).
Hepatitis (2 papers, 2013 to 2016). Inflammation of the liver. "To investigate the role of Gpx1 in experimental T cell-mediated hepatitis, we injected Con A into WT and Gpx1 KO mice." (PMID 27124582, 2016). "Using a combination of reverse transcription and real-time polymerase chain reaction, expression of the glutathione peroxidase and glutathione reductase genes (Gpx1 and Gsr) was analyzed by the determination of their respective mRNAs in the rat liver tissue under toxic hepatitis conditions." (PMID 23554813, 2013).
Huntington disease (2 papers, 2017). Huntington disease (HD) is a rare neurodegenerative disorder of the central nervous system characterized by unwanted choreatic movements, behavioral and psychiatric disturbances and dementia. "We also found many differentially expressed genes related to the Huntington disease (HD) pathway in both areas of the MPS II mouse model; among these, Bbc3, Bdnf, Crebbp, Dctn1, Dlg4, Gpx1, Grin1, Grin2b, Itpr1, and Pparg are up-regulated, while Dnaic2, Dnali1, Hap1, and Vdac2 are down-regulated." (PMID 28513549, 2017).
hypothyroidism (2 papers, 2012 to 2024). Abnormally low levels of thyroid hormone. "The genes Sod1, Sod2 and Gpx1 were reduced in tests on rats with hypothyroidism, which is similar to previous studies conducted on this species." (PMID 38338793, 2024). "Hypothyroidism increased apoptosis index, TBARS and LOOH concentrations, and reduced testicular gene expression of Sod1, Sod2 and Gpx1, as well as the expression of Grp78, Atf6, Ho1 and Chop." (PMID 38338793, 2024). "Although Kp10 did not change the low expression of these genes caused by hypothyroidism, a significant increase in the immunostaining of SOD1 and GPX1/2 was observed after treatment, highlighting their antioxidant effects in tests on hypothyroid rats." (PMID 38338793, 2024).
influenza (2 papers, 2011 to 2023). An acute viral infection of the respiratory tract, occurring in isolated cases, in epidemics, or in pandemics; it is caused by serologically different strains of viruses (influenzaviruses) designated A, B, and C, has a 3-day incubation period, and usually lasts for 3 to 10 days. "With the increase of the expression of the antioxidant enzymes GPx1 and TrxR1, apoptosis associated with influenza-mediated oxidative damage in lung tissue was also mitigated." (PMID 37064873, 2023). "As an anti-influenza drug, RuSe plays an antiviral role and also acts as a drug carrier to deliver selenium to the organism, regulate the selenium proteins GPx1 and TrxR1 in vivo, and play an antioxidant role in inhibiting ROS-mediated apoptosis." (PMID 37064873, 2023). "There were no significanteffects of the influenza vaccine on platelet total GPx1 activity, week 10compared with week 12 data, for any of the groups." (PMID 21445287, 2011).
ischemia reperfusion injury (2 papers, 2022 to 2024). Adverse functional, metabolic, or structural changes in ischemic tissues resulting from the restoration of blood flow to the tissue (reperfusion), including swelling; hemorrhage; necrosis; and damage from free radicals. "Se nanoparticles may alleviate AKI induced by ischemia reperfusion injury by upregulated the (GPx)-1 levels and suppressed NLRP3 inflammasome." (PMID 38486133, 2024).
laryngeal squamous cell carcinoma (2 papers, 2019 to 2020). A squamous cell carcinoma that arises from the larynx. "Such as, the expression levels of GPX1 were highly expressed and predicted poor prognosis in laryngeal squamous cell carcinoma." (PMID 31844035, 2019).
liver failure (2 papers, 2020 to 2024). A liver disease characterized by the liver losing or has lost all of its function. "Researchers observed that glutathione peroxidase 1 (GPX1) derived from hUC-MSCs exosomes effectively lower the levels of ROS and malondialdehyde (MDA) in liver and inhibit apoptosis induced by oxidative stress in liver failure." (PMID 38431569, 2024).
male infertility (2 papers, 2023 to 2025). The inability of the male to effect fertilization of an ovum after a specified period of unprotected intercourse. "Among the family of GPXs, the activity of GPX1-4 is dependent on selenium, of which GPX4 is an important structural protein that is very abundant in sperm mitochondria (about 50% of sperm mid-segment proteins), while when it is absent it leads to male infertility." (PMID 37174590, 2023).
malignant pleural mesothelioma (2 papers, 2021 to 2022). A malignant neoplasm that arises from mesothelial cells in the pleura and shows a diffuse growth pattern. "GPX1 mRNA level is significantly elevated in malignant pleural mesothelioma tissues compared to normal adjacent pleural tissues, and the high GPX1 level is associated with a short survival time." (PMID 35626163, 2022).
mastitis (2 papers, 2022 to 2025). Inflammation of breast tissue during lactation or postpartum due to an obstructed duct or infection. "As far as we are concerned, this is the first study revealing SNPs in SELL, ABCG2, SLC11A1, FEZL, SOD1, CAT, GPX1, and AhpC/TSA genes as candidates for mastitis tolerance/susceptibility in Holstein and Brown Swiss dairy cows." (PMID 35737346, 2022). "In the present study, a real-time PCR was carried out to quantify the mRNA level of SELL, ABCG2, SLC11A1, FEZL, SOD1, CAT, GPX1, and AhpC/TSA genes in tolerant and susceptible Holstein and Brown Swiss dairy cows to mastitis." (PMID 35737346, 2022). "PCR-DNA sequencing of SELL, ABCG2, SLC11A1, FEZL, SOD1, CAT, GPX1, and AhpC/TSA revealed nucleotide sequence variations in the form of SNPs associated with mastitis tolerance/susceptibility in investigated Holstein and Brown Swiss dairy cows." (PMID 35737346, 2022). "Consequently, the aim of the current work was to revealing the association of SNPs and expression profile of SELL, ABCG2, SLC11A1, FEZL,SOD1,CAT,GPX1, and AhpC/TSA genes with mastitis tolerance/susceptibility in Holstein and Brown Swiss dairy cows." (PMID 35737346, 2022). "Mastitis-affected sheep had significantly reduced expression levels of the genes CAT, GPX1, ATOX1, GST, and Nrf2 compared to resistant ewes." (PMID 40542007, 2025). "Consequently, SELL, ABCG2, SLC11A1, FEZL, SOD1, CAT, GPX1, and AhpC/TSA regulation mechanisms are well understood in the mastitis tolerant and affected Holstein and Brown Swiss dairy cows." (PMID 35737346, 2022). "In the current investigation, qRT-PCR was used to measure the levels of antioxidant (CAT, GPX1, Keap1, OXSR1, ATOX1, GST, and Nrf2) and immune (IFN-γ, IL-4, TNF-α, MYD88, CCL5, TLR4, TLR9, LTF, and PRLR) genes in Barki ewes that were resistant and non-resistant to mastitis." (PMID 40542007, 2025).
metastatic cancer (2 papers, 2020 to 2022). A carcinoma which has spread from the original site of growth to another anatomic site. "When overexpressed, GPx1 has been shown to protect cancer cells from highly oxidizing anti-cancer agents; the level of GPx1 also appears to correlate directly with advanced metastatic cancers." (PMID 32414091, 2020). "In our RNA-seq data, GPX1 and GPX4 were reduced in neutrophils incubated in metastatic cancer CM, suggesting neutrophils in a metastatic environment cannot regulate H2O2 levels." (PMID 35604506, 2022).
metastatic disease (2 papers, 2021 to 2024). "The expression of various antioxidants, including PRX1, GPX1, UBE2N, and AIF1, was significantly higher in metastatic tumors." (PMID 39795567, 2024).
migraine (2 papers, 2019 to 2022). "Genotypic and allelic frequency distribution analysis of the GPX1 rs1050450 variant in migraineurs according to the typical duration of migraine attacks (≤24 vs. >24 h)." (PMID 36698892, 2022).
Myalgia (2 papers, 2022 to 2025). "Furthermore, the combined presence of GSTP1 Ile and GSTO1 Ala alleles exhibited cumulative risk regarding long-COVID myalgia in carriers of the combined GPX1 LeuLeu/GPX3 CC genotype." (PMID 35624818, 2022). "The combined effect of risk genotypes (GSTP1 AB IleIle, GSTO1 AlaAla, GPX1 LeuLeu, and GPX3 CC) markedly increased the probability of myalgia, suggesting a cumulative genetic burden." (PMID 40867811, 2025).
nonalcoholic steatohepatitis (2 papers, 2021). "A study in the nonalcoholic steatohepatitis model showed that RORα reduced ROS levels in hepatocytes and suppressed hepatic oxidative stress, which is accompanied with induction SOD2 and Gpx1." (PMID 34639006, 2021).